SLC25A4 (solute carrier family 25 member 4)
Diseases named in the same sentence as SLC25A4 in open-access papers (continued):
Sharing a sentence is not in itself a finding about the gene and the disease.
melanoma (1 paper, 2023). A malignant, usually aggressive tumor composed of atypical, neoplastic melanocytes. "Although sequence variations in SLC25A4 and SLC45A2 have been described as associated with skin hypopigmentation and a higher risk for melanoma, their gene regulation mechanism is still unclear and should be further investigated." (PMID 37397501, 2023).
membranous nephropathy (1 paper, 2024). "Regrettably, there have been no reported associations between SLC25A4 and membranous nephropathy." (PMID 38846934, 2024).
mood disorder (1 paper, 2011). A cognitive disorder a disturbance in which the person's mood is hypothesized to be the main underlying feature. "So far, rare variants of POLG1, C10orf2 and SLC25A4 have been reported in inherited PEO pedigrees with frequent comorbidity of mood disorders." (PMID 21951382, 2011).
neuroblastoma (1 paper, 2023). Neuroblastoma (NB) is the most common solid, extracranial childhood tumor. "However, these phenotypes were not shared by SLC25A1-null neuroblastoma cells or SLC25A4-null cells, even though these cells also displayed increased APOE expression and secretion." (PMID 37171075, 2023).
osteoporosis (1 paper, 2025). A condition of reduced bone mass, with decreased cortical thickness and a decrease in the number and size of the trabeculae of cancellous bone (but normal chemical composition), resulting in increased fracture incidence. "In summary, our study reveals that Sirt5-mediated desuccinylation of Slc25a4 at K147 constitutes a critical regulatory mechanism in osteoporosis pathogenesis." (PMID 41243032, 2025). "To determine whether Sirt5-mediated protection against osteoporosis specifically requires Slc25a4 desuccinylation, we performed genetic complementation experiments in Sirt5-deficient and wild-type backgrounds." (PMID 41243032, 2025).
sarcoidosis (1 paper, 2023). Sarcoidosis is a multisystemic disorder of unknown cause characterized by the formation of immune granulomas in involved organs. "The SLC25A4 epitope is highly homologous to the "FLAGGVAGTV" sequence from the core binding region and anchor residue of the LysM peptidoglycan-binding domain-containing protein expressed in C. acnes, which has been implicated in sarcoidosis incidence." (PMID 37957180, 2023).
stomach adenocarcinoma (1 paper, 2022). "In stomach adenocarcinoma, SLC25A7 had increased expression while SLC25A4 was decreased." (PMID 36254139, 2022).
uterine corpus endometrial carcinoma (1 paper, 2022). A endometrial carcinoma (disease) that involves the body of uterus. "In uterine corpus endometrial carcinoma, the mutation of SLC25A4, SLC25A25, and SLC25A27 had certain impacts on their expression." (PMID 36254139, 2022).
mitochondrial disease (7 papers, 2011 to 2022). "Mutations in SLC25A4 encoding the mitochondrial ADP/ATP carrier AAC1 are well-recognized causes of mitochondrial disease." (PMID 27693233, 2016).
tumor (7 papers, 2020 to 2025). "According to a recent study, tumor-associated macrophages (TAMs) may regulate the heme oxygenase (HO-1) expression level by controlling SLC25A4, promoting M2 macrophage polarization, and enhancing tumor metastasis." (PMID 38644410, 2024). "Given the importance of migratory and invasive features of tumor cells in tumor development and metastasis, wound healing and Transwell assessments were next conducted on SLC25A4 knockdown cells." (PMID 38957810, 2024). "SLC25A4 results significantly upregulated in 2 cancer tissues and significantly downregulated in 14 cancer tissues, out of the 21 “tumor vs. normal” tissue pairs." (PMID 33396658, 2020). "Based on these findings, SLC25A4 was strongly diminished among the tumor group." (PMID 38957810, 2024). "As shown, of the various tumor pathological grades, the expression levels of SLC25A4 (P < 0.01), SLC25A11 (P < 0.0001), SLC25A24 (P < 0.01), SLC25A37 (P < 0.01), SLC25A42 (P < 0.01), SLC25A43 (P < 0.0001), SLC25A44 (P < 0.05) and SLC25A45 (P < 0.05) were significantly different." (PMID 36514121, 2022). "TAMs might regulate the expression level of HO-1 by regulating SLC25A4 to promote the M2 polarization of macrophages and enhance the ability of tumor metastasis." (PMID 36254139, 2022). "Furthermore, cell function assays revealed that increased expression of SLC25A4 significantly reduced OS cell proliferation, migration, and invasion, while enhancing apoptosis, indicating that SLC25A4 was involved in tumorigenesis, tumor progression, and metastasis." (PMID 38957810, 2024). "Thus, the decreased expression of SLC25A4 might lead to aberrant metabolism, participating in tumor progression." (PMID 36254139, 2022). "Among them, TAZ was up-regulated in tumor tissue compared with para-cancerous tissue, and the expression of the remaining eight genes (including SLC25A4, SLC25A5, PARK, PINK1, MFN2, HUWE1, VPS13D, and LRBA) was down-regulated in tumor tissue." (PMID 38373978, 2024). "Timer2 analysis shows that SLC25A4, SLC25A5, and SLC25A6 genes are differentially expressed in 16, 12, and 9 tissues out of the available 21 “tumor vs. normal” tissue pairs, respectively." (PMID 33396658, 2020). "Furthermore, the results confirm the involvement of SLC25A4 in the development of CRC and its silencing in all stages and the reduced expression of SLC35A1 in this tumor." (PMID 41465541, 2025).
cancer (6 papers, 2020 to 2025). A tumor composed of atypical neoplastic, often pleomorphic cells that invade other tissues. "Pan-cancer analysis of the SLC25 family suggests that SLC25A4 is linked to multiple oncogenic pathways, including the PI3K-AKT-MTOR pathway, MYC-TARGETS-V1 pathway, MYC-TARGETS-V2 pathway, and MTORC1 pathway." (PMID 38846934, 2024). "The frequencies of SLC25A4 mutations in pan-cancer were 3%, and they were typically missense mutation, splice mutation, truncating mutation, amplification, and deep deletion." (PMID 38957810, 2024). "Furthermore, pan-cancer analysis revealed that SLC25A4 expression was reduced in most tumors, and the cBioPortal database indicated that genetic alterations in SLC25A4 were strongly linked to OS patient prognosis." (PMID 38957810, 2024). "SLC25A4 expression in pan-cancer was then explored, which indicated a decrease in the SLC25A4 expression in most tumors." (PMID 38957810, 2024). "In conclusion, we identified PIK3R1, CCND1, TERF2IP, SLC25A4, CAPN2, and TXN as potential markers associated with both cancer and MN." (PMID 38846934, 2024). "Whole genome pan-cancer analysis (ICGC/TCGA, Nature 2020) was performed to identify the genetic alterations and mutations in SLC25A4 via the cBioPortal database." (PMID 38957810, 2024). "The study would provide theoretical basis for their application as potential targets of cancer therapy including SLC25A4, SLC25A7, and SLC25A23." (PMID 36254139, 2022). "Several genes were selected for the validation of expression in fresh cancer tissue by qPCR and IHC including SLC25A4, SLC25A7, and SLC25A23." (PMID 36254139, 2022). "Among them, the CNV of SLC25A4 had statistical significance in most cancer, which was positively correlated with SLC25A4 expression." (PMID 36254139, 2022). "However, several genes such as SLC25A4 and SLC25A5 showed low mutation frequency in most cancer with an overall average mutation rate of 0.100189." (PMID 36254139, 2022). "The protein expression of SLC25A4, SLC25A5, and SLC25A6 was consistent in top 10 common cancer types." (PMID 36254139, 2022). "Among the various cancers examined, SLC22A6, SLC22A7, SLC22A13, SLC25A4, and SLC34A1 were significantly downregulated, while SLC44A4 showed different expression patterns in different cancers (upregulated or downregulated)." (PMID 32461965, 2020). "We used the Oncomine database to analyze the expression levels of SLC22A6, SLC22A7, SLC22A13, SLC25A4, SLC34A1, and SLC44A4 in various cancers and their normal tissues." (PMID 32461965, 2020). "The expression levels of SLC22A6, SLC22A13, SLC25A4, SLC34A1, and SLC44A4 were significantly correlated with the clinical stage of the cancer." (PMID 32461965, 2020). "Our analysis led to the identification of PIK3R1, CCND1, TERF2IP, SLC25A4, CAPN2, and TXN as hub genes, which could potentially serve as targets for interventions in both MN and cancer." (PMID 38846934, 2024). "SLC25A4 and SLC25A5 might be involved in some carcinogenic pathways and metabolic pathways regulated by genetic variation, participating in cancer initiation and development." (PMID 36254139, 2022). "Combining previous researches and our results, we speculated SLC25A4, SLC25A5, SLC25A9, and SLC2512 might participate in metabolic reprogramming and cancer initiation and development via these oncogenic and metabolic pathways." (PMID 36254139, 2022). "In cancer tissues, SLC25A4 and SLC44A4 proteins did not change significantly in terms of staining, intensity, and quantity." (PMID 32461965, 2020).
myopathy (6 papers, 2018 to 2025). A disease of the muscle in which the muscle fibers do not function properly. "Here, we report that the de novo dominant variant p.Lys33Gln in SLC25A4 is clinically associated with mild myopathy despite significant mitochondrial pathology in muscle biopsy and functional data showing abolished ADP/ATP exchange in vitro." (PMID 30046662, 2018). "In addition, the gene encoding solute carrier family 25 (SLC25A4) slightly decreased as the myopathy progressed." (PMID 32612536, 2020). "Gene expression levels of mitochondrial ion transporters, including VDAC1,2,3, SLC25A4, and SLC25A6, were not significantly changed, though all appeared elevated in the myopathy-derived skin fibroblasts." (PMID 35216315, 2022).
infection (1 paper, 2024). The state of being infected such as from the introduction of a foreign agent such as serum, vaccine, antigenic substance or organism. "In this study, we show that infection with RABV or overexpression of its M protein can disrupt mitochondrial metabolism by binding to Slc25a4." (PMID 38349129, 2024).
infectious disease (1 paper, 2025). A disorder directly resulting from the presence and activity of a microbial, viral, or parasitic agent in humans. "SLC25A4 also participates in various Reactome pathways, including Infectious Disease (HSA-5663205), HIV Infection (HSA-162906), and Disease (HSA-1643685)." (PMID 40649814, 2025).
SLC25A4 also shares sentences with these, for which no sentence is quoted: Mitochondrial myopathy (6 papers); familial hypertrophic cardiomyopathy (2); ischemia (2); lactic acidosis (2); neurological disease (2); prostate carcinoma (2); acute monocytic leukemia (1); Arts syndrome (1); breast carcinoma (1); cataract (1); depression (1); Desminopathy (1); diabetes (1); Encephalopathy (1); endocervical adenocarcinoma (1); genetic disorder (1); heart failure (1); Hydrocephalus (1); Insulin resistance (1); intestinal cancer (1); lung squamous cell carcinoma (1); male infertility (1); metabolic disorders (1); mitochondrial DNA depletion syndrome (1); multiple acyl-CoA dehydrogenase deficiency (1); myocarditis (1); neurodevelopmental disorder (1); Obesity (1); ophthalmoplegia (1); osteosarcoma (1).
A further 12 diseases each share a sentence with SLC25A4 in 1 paper.